GDF15 (growth differentiation factor 15)
Diseases named in the same sentence as GDF15 in open-access papers (continued):
Sharing a sentence is not in itself a finding about the gene and the disease.
atherosclerosis (continued). "The growth differentiation factor-15 (GDF-15) may be involved in atherosclerosis." (PMID 34539804, 2021). "Thus, GDF-15 may suppress atherosclerosis and plaque formation by inhibiting lipoprotein accumulation and inflammation activation." (PMID 34539804, 2021). "GDF-15 may have a protective effect on atherosclerosis process." (PMID 33115406, 2020). "A hypothesis has been established on an inhibitory role for GABA in atherosclerosis, acting as a potential urinary marker of cardiovascular risk when it is diminished, which is in line with our previous observations in GDF15 (growth differentiation factor 15) and ECP (eosinophil cationic protein)." (PMID 32914213, 2020). "Thus, GDF15 functions as a pro- and anti-inflammatory factor in the development and progression of atherosclerosis, and its activity may depend on the pathophysiological environment and progression stage." (PMID 32222153, 2020). "Regarding the role of GDF15 in cardiovascular health, studies in rodents suggest GDF15 may have a protective role in agonist-induced hypertrophy, ischemia/reperfusion injury, and in atherosclerosis." (PMID 31650091, 2019). "GDF15 may have utility as a biomarker for a variety of diseases and may also identify NTDT patients at increased risk of pulmonary and cardiovascular complications as well as subclinical atherosclerosis." (PMID 30834265, 2019). "Furthermore, GDF15-induced senescence in HAECs suggested that GDF15 released in senescent or irradiated endothelial cells might contribute to the pathogenesis of atherosclerosis via its pro-senescent activity." (PMID 26909594, 2016). "In addition, injury, oxidative stress and atherosclerosis can increase secretion of GDF-15." (PMID 26075263, 2015). "Although the functions of GDF15 and Lp-PLA2 in the lung homeostasis are still unknown, their association to cancer, atherosclerosis, tissue injury or lipid metabolism makes them important research targets in the context of cigarette smoke-related lung diseases." (PMID 24663285, 2014). "Because hypercholesterolemia and subsequent increase in triglyceride levels are associated with an increased risk of atherosclerosis, we conclude that the inhibition of lesion progression in the absence of GDF‐15 cannot be due to a regulation of plasma lipid levels." (PMID 23316317, 2012). "Members of the transforming growth factor-β superfamily, such as growth differentiation factor 15 (GDF-15), are potent regulators of vascular remodeling and play key roles in atherosclerosis." (PMID 40988271, 2025). "Likewise, GDF15 was positively associated with an atherogenic profile, particularly with the number of very-low-density lipoproteins (VLDL) particles and its cholesterol and triglyceride content, and with an indicator of subclinical atherosclerosis (i.e., carotid intima–media thickness (cIMT))." (PMID 40076667, 2025). "The sex- and age-adjusted ORs (95%CIs) of atherosclerosis were 1.95 (1.09, 3.48) for high GDF-15 and 0.83 (0.37, 1.88) for low GDF-15." (PMID 39019981, 2024). "Other promising mortality and disease progression predictors in patients with atherosclerosis and CAD are growth differentiation factor 15 (GDF-15), T-cell immunoglobulin, and mucin domain-3 (TIM-3)." (PMID 39330316, 2024). "In model 2, the adjusted ORs (95%CIs) of atherosclerosis were 1.93 (1.08, 3.46) for high GDF-15 and 0.84 (0.36, 1.92) for low GDF-15, while in model 3, the corresponding values were 2.07 (1.12, 3.82) and 0.82 (0.35, 1.87)." (PMID 39019981, 2024).
atherosclerosis (continued). "Furthermore, GDF15, in combination with oxLDL, positively regulates the expression of autophagy‐related proteins such as Atg5, p62 and the Atg12/Atg5 protein complex and elicits p62 accumulation in human macrophages, thus promoting lipid accumulation and, therefore, atherosclerosis development." (PMID 36992609, 2023). "In macrophages, GDF-15 induces the expression of ABCA1 by triggering the PI3-K related pathway, and then indirectly results in atherosclerosis." (PMID 35842724, 2022). "For detailed investigations, we used an in vitro human atherosclerosis MΦ model, and in vivo GDF-15−/−/ApoE−/− mice under CED, to study the role of GDF-15 on autophagic processes in atherosclerotic lesions." (PMID 34571994, 2021). "However, the role of GDF-15 in atherosclerosis remains unclear." (PMID 34539804, 2021). "In particular, a study in mouse models indicates that the deletion of haematopoietic GDF15 reduces CCR2 expression and chemotaxis and improves plaque stability, with beneficial effects against atherosclerosis." (PMID 32757036, 2020). "In this study, we investigated the effect of GDF-15 level on the extent and severity of atherosclerosis in patients with peripheral artery disease (PAD) without obstructive coronary artery disease." (PMID 40988271, 2025). "However, the role of GDF15, as for other TGF family members, in atherosclerosis, remains contradictory." (PMID 40837873, 2025). "GDF-15 was shown to signal through glial cell-derived neurotrophic factor (GDNF) family α-like (GFRAL) receptors in cancer cells and brainstem neurons, but clearly, GDF-15 signalling in cells related to atherosclerosis development has not been explored yet." (PMID 38396781, 2024). "In summary, serum GDF-15 concentrations in healthy subjects of all ages and in patients with varying degrees of atherosclerosis are not well defined." (PMID 38396781, 2024). "In a previous study involving patients at an advanced stage of atherosclerosis, GDF-15 did not relate to plaque characteristics such as macrophage amount, calcification, intraplaque fat, and hemorrhage." (PMID 39780955, 2024). "Our data suggest that circulating GDF-15 levels and NLR might serve as biomarkers of subclinical atherosclerosis in patients with psoriasis." (PMID 34728734, 2021). "GDF-15 belongs to the transforming growth factor-β (TGF-β)/bone morphogenetic proteins (BMPs) superfamily, which are potent regulators of vascular development and vascular remodeling and play a key role in atherosclerosis and restenosis." (PMID 34539804, 2021). "Previous studies demonstrated that a higher circulating level of GDF15 was an independent predictor of CKD mortality after multivariate adjustment, and correlated with the severity of atherosclerosis, hypoalbuminemia, inflammation, HD vintage, and protein-energy wasting." (PMID 33670413, 2021). "Therefore, we used a complete GDF‐15 knockout mouse developed in our laboratory and crossbred it with apoE−/− mice, to study putative functions of GDF‐15 in atherosclerosis." (PMID 23316317, 2012). "In addition, GDF-15 was able to inhibit the oxLDL-induced inflammatory response (including the downregulation of IL-6, IL-8, MCP-1, and MMP-9 in oxLDL-treated macrophages), which promotes the initiation and development of atherosclerosis." (PMID 38396781, 2024). "GDF-15 levels have been found to be elevated in patients with SCD, thalassemia (both major and intermediate), and the compound heterozygotes HbS/βthal and to correlate with endothelial dysfunction and atherosclerosis in the transfusion-dependent form (tdt) beta-thalassemia." (PMID 38203404, 2023). "However, there have been no reports about the association between atherosclerosis as evaluated by CIMT and serum GDF-15 concentration in a comparative healthy general population." (PMID 37371667, 2023).
atherosclerosis (continued). "Increased GDF15 levels were reported to participate in the pathogenesis of metabolic diseases such as nonalcoholic fatty liver disease (NAFLD) and type 2 diabetes, cardiovascular disease such as hypertrophy and atherosclerosis, and some type of cancers such as PCa, breast cancer and gastric cancer." (PMID 35853851, 2022). "Further, we investigated the might mechanism of GDF-15 in oxLDL-induced lipoprotein accumulation and inflammation in macrophages in order to provide new clues for further understanding the role and mechanism of GDF-15 in atherosclerosis." (PMID 34539804, 2021). "A protective role of GDF-15 in atherosclerosis might be compatible with the negative link between GDF-15 levels and subclinical vascular inflammation observed in our study." (PMID 34728734, 2021). "Because the stability of plaque plays a blocking effect on the development of atherosclerosis and the deficiency of GDF-15 expression can improve the stability of plaque, some studies believe that the lack of GDF-15 is conducive to the body's resistance to vascular injury and inflammation." (PMID 34539804, 2021). "However, it is not known how GDF-15 acts in the advanced stages of atherosclerosis that we often find in human disease." (PMID 23800095, 2013). "Thus, GDF-15 appears to be a prognostic biomarker of CVD co-morbidity, but not a predictive biomarker of COPD outcomes, in agreement with recent findings suggesting that endothelial dysfunction predicts atherosclerosis in COPD, but does not contribute to airflow limitation." (PMID 28245821, 2017).
myocardial infarction (112 papers, 2012 to 2026). Gross necrosis of the myocardium, as a result of interruption of the blood supply to the area, as in coronary thrombosis. "In the context of CAD, elevated GDF-15 levels have been linked to worse clinical outcomes, including increased risks of myocardial infarction (MI), cardiovascular death, and all-cause mortality." (PMID 41590509, 2026). "Elevated GDF-15 levels are associated with an increased risk of developing HF, including post-myocardial infarction HF." (PMID 40244022, 2025). "GDF15 deficiency in mouse models of heart attack or ischemia leads to larger infarcts and greater cardiomyocyte apoptosis." (PMID 40837873, 2025). "Elevated circulating levels of GDF15 are associated with a range of cardiovascular conditions, including heart failure, myocardial infarction, and atherosclerosis." (PMID 40407975, 2025). "This study aimed to clarify the mechanisms underlying the cardioprotective effects of GDF-15 in myocardial infarction." (PMID 41023695, 2025). "Myocardial infarction, a condition associated with CAD, is associated with manydeaths and shows upregulation of GDF-15 after acute myocardial infarction." (PMID 39077481, 2023). "This study provided genetic evidence, suggesting that circulating GDF-15 levels are significantly linked to the increased risk of AF, coronary artery disease, myocardial infarction, and cardioembolic stroke." (PMID 36337899, 2022). "High serum levels of GDF-15 predict risk of mortality in patients admitted with myocardial infarction." (PMID 36361969, 2022). "GDF-15 plays a role in the evaluation of a variety of CVDs, such as risk stratification after myocardial infarction (MI), atrial fibrillation, the prognosis of heart failure, and prediction of bleeding events during anticoagulant therapy." (PMID 35757636, 2022). "GDF-15 levels were associated with cardiovascular pathologies such as heart failure, hypertrophy, atherosclerosis, endothelial dysfunction and recurrent myocardial infarction." (PMID 34821692, 2021). "Based on the instruments, circulating GDF-15 levels significantly linked to the increased risk of cardioembolic stroke, atrial fibrillation, coronary artery disease and myocardial infarction." (PMID 33115406, 2020). "Growth differentiation factor-15 (GDF-15) is also a member of the TGF-β family that has been implicated in suppression of inflammation after myocardial infarction." (PMID 33041853, 2020). "It is reported that GDF-15 are associated with increased risks for patients with acute myocardial infarction." (PMID 29791474, 2018). "GDF-15 is associated with NT-proBNP and cTnT levels at presentation in those myocardial infarction patients." (PMID 27311391, 2016). "A recent study found evidence that GDF-15 is associated with infarct size in experimental heart attack models." (PMID 26075263, 2015). "Regarding the top over-expressed genes, growth and differentiation factor 15 (GDF-15) encodes a cytokine which has been involved in a variety of processes including reduced risk of miscarriage and myocardial infarction." (PMID 24484525, 2014). "GDF-15 is described as a novel biomarker with a high impact on risk stratification and prognostic value in myocardial infarction, chronic heart failure, and pulmonary embolism." (PMID 23800095, 2013). "Consistent studies have reported the association of GDF-15 with LVH in parameters of LVH in patients with myocardial infarction." (PMID 23071585, 2012). "Finally, the analysis from the PLATO study revealed that higher GDF15 levels were associated with increased risk of stroke, myocardial infarction, and mortality, thus confirming previous reports." (PMID 41303556, 2025). "Previously, GDF15 has been consistently reported as being upregulated in response to neurodegeneration and associated with elevated risk for several other age‐related diseases (e.g., coronary artery disease, myocardial infarction, cardiometabolic stroke)." (PMID 41274863, 2025).
myocardial infarction (continued). "We also investigated its direct cardiac effects in both in vivo and ex vivo models of I/R using recombinant GDF15 concentrations relevant to patients with a high CV risk, to assess the potential suitability of rGDF15 as a therapeutic strategy in the context of myocardial infarction." (PMID 38839839, 2024). "Additionally, increased levels of GDF15 have been reported following ischemic-reperfusion injuries or myocardial infarction, which are often linked to the use of extracorporeal circulation." (PMID 39766300, 2024). "Besides its anorexigenic effect and its effect on glucose metabolism, GDF-15 has also been proposed as a biomarker for increased mortality risk and recurrent myocardial infarction (MI) after acute coronary syndrome." (PMID 39000420, 2024). "This usually results inheart failure, as well as an increased risk of myocardial infarction.The hypertrophic signaling effect mediated by GDF-15 via the epidermal growthfactor receptor (EGFR), PI3K, AKT, ERK, as well as SMAD proteins is controversialin this regard." (PMID 39077481, 2023). "High serum levels of GDF15 have been associated with acute myocardial infarction and have been correlated with levels of other cardiovascular risk biomarkers including troponin-T, N-terminal probrain natriuretic peptide, and CRP possibly suggesting a link between GDF15 and inflammation." (PMID 29967567, 2018). "However, it should be noted that high levels of GDF15 were recently associated with a poorer prognosis in patients with acute myocardial infarction." (PMID 24069374, 2013). "In the PLATO (PLATelet inhibition and patient Outcomes) trial, GDF-15 was an independent risk factor for major bleeding across different bleeding locations, as well as for the composite endpoint of cardiovascular death, spontaneous myocardial infarction and stroke in ACS patients." (PMID 36836162, 2023). "We also found direct associations of all 5 markers with myocardial infarction (MI) risk, and of GDF-15, NT-proBNP, CRP and cystatin-C with stroke risk." (PMID 34935094, 2022). "In mouse models of nonalcoholic steatohepatitis and myocardial infarction, the knockout of GDF15 can result in increased fibrosis, leading to higher mortality." (PMID 41474228, 2026). "In summary, our study elucidates GDF15’s multifaceted protective mechanisms in myocardial infarction, including regulation of AMPK signaling, mitochondrial function, reactive oxygen species production, and inflammatory responses." (PMID 41023695, 2025). "During pathological events such as myocardial infarction, ischemia–reperfusion injury, and metabolic disorders, GDF15 expression increases in multiple tissues, including the kidney, heart, skeletal muscles, and adipose tissue." (PMID 40837873, 2025). "In acute coronary syndrome (ACS), GDF-15 predicts recurrence of myocardial infarction and cardiac death." (PMID 40244022, 2025). "In the context of myocardial injury, GDF15 expression is markedly upregulated in infarcted myocardium compared to healthy tissue and is elevated in the bloodstream following acute myocardial infarction." (PMID 40806859, 2025). "Future studies should focus on translational research to evaluate the clinical efficacy of GDF-15-based therapies in myocardial infarction patients." (PMID 41023695, 2025). "In myocardial infarction and ischemia–reperfusion injury, GDF15 exerts a cardioprotective effect by reducing cell death and limiting tissue damage." (PMID 40837873, 2025). "Growth differentiation factor-15, a stress-responsive cytokine, has been involved in cardiac pathophysiology, but its exact role in myocardial infarction remains controversial." (PMID 41023695, 2025). "Therapeutic administration of exogenous GDF-15 reduces myocardial injury, hypoxic stress, and fibrosis after myocardial infarction, suggesting its potential as a therapeutic target." (PMID 41023695, 2025).